FGF5 (fibroblast growth factor 5)
Diseases named in the same sentence as FGF5 in open-access papers (continued):
Sharing a sentence is not in itself a finding about the gene and the disease.
brain tumors (1 paper, 2025). "Thus, in-depth studies are needed to elucidate the exact mechanisms triggered by abnormally high levels of FGF5 in the developing cerebellum, particularly since Fgf5 overexpression is known to drive cancer development and progression, including brain tumors." (PMID 39835775, 2025).
central obesity (1 paper, 2020). "Therefore, we used the 6 G × E tests to investigate whether the influence of FGF5 can be modified by an indicator of central obesity, WHR." (PMID 32457790, 2020).
cocaine addiction (1 paper, 2020). "Twelve DEGs (Myct1, Gm21860, Ninj2, Fam183b, Lars2, Alkbh1, Fgf5, Frmd7, Tm6sf2, Wnt6, Batf3, and Clca1) were found to be regulated inversely among the overlap genes, which may be possible targets of RPA to disrupt the cocaine addiction process." (PMID 32489401, 2020).
corticobasal syndrome (1 paper, 2019). Corticobasal syndrome (CBS) is a rare neurodegenerative disease characterized by multifaceted motor system dysfunctions and cognitive defects such as asymmetric rigidity, bradykinesia, limb apraxia, and visuospatial dysfunction. "Disease-specific analyses revealed lower group levels of FGF-5, FGF-19 and SPOCK1 in multiple system atrophy compared with progressive supranuclear palsy and corticobasal syndrome." (PMID 30867224, 2019).
diabetic retinopathy (1 paper, 2020). "Transfection of miR-145-5p inhibitor (inhibits fibroblast growth factor 5, FGF5) in RGC-5 cells exposed to high glucose, as in an in vitro diabetic retinopathy model, produces a decrease in TNF-α and IL-6 on these cells and also reduces apoptosis, keeping an elevated cell proliferation capacity." (PMID 32231131, 2020).
endometrial cancer (1 paper, 2023). Primary or metastatic malignant neoplasm involving the endometrium (mucous membrane that lines the endometrial cavity). "Whether secretion of growth factors (TGFβ, GAS6, FGF5 and HGF), cytokines and chemokines (IL-6, CXCL9) from CAFs,32 may affect aggressiveness and thereby associate with recurrence of endometrial cancer, is not known and could be investigated in future studies." (PMID 37146405, 2023).
epilepsy (1 paper, 2023). A brain disorder characterized by episodes of abnormally increased neuronal discharge resulting in transient episodes of sensory or motor neurological dysfunction, or psychic dysfunction. "Similar to FGF5, FGF7 also has a putative positive role in epilepsy as Fgf7-deficient mice exhibit enhanced seizure activity." (PMID 36650549, 2023).
hair disorders (1 paper, 2021). "Since the aptamers have high affinity and specificity to FGF5 and inhibit FGF5-induced cell proliferation, they may be candidates for therapeutic use with FGF5-related diseases or hair disorders." (PMID 33536494, 2021). "Therefore, to develop therapeutic candidates for FGF5-related diseases or hair disorders, we performed SELEX and obtained anti-FGF5 aptamers that have high affinity and specificity to FGF5 and inhibit FGF5-induced cell proliferation." (PMID 33536494, 2021).
head and neck squamous cell carcinoma (1 paper, 2025). A squamous cell carcinoma that arises from any of the following anatomic sites: lip and oral cavity, nasal cavity, paranasal sinuses, pharynx, larynx, and salivary glands. "To explore the relationship between FGF5 expression and DNA methylation, we analyzed head and neck squamous cell carcinoma (HNSC) data from TCGA." (PMID 40001587, 2025).
liver disease (1 paper, 2025). "Although no literature has shown so far that PLAU, FGF5, and IL24 affect HIRI by regulating immune cell infiltration, studies have reported the important regulatory roles of these two genes in the immune microenvironment and immune response in liver disease." (PMID 40705804, 2025).
myeloid leukemia (1 paper, 2017). A clonal proliferation of myeloid cells and their precursors in the bone marrow, peripheral blood, and spleen. "Many of those genes inhibited by SID peptide treatment (CD44, TGFβR2, LEF1, TCF7L2, FGF2, FGF5, ID2, PIK3R3) are known as direct TGIF1 targets in myeloid leukemia or embryonic stem cells." (PMID 29179446, 2017).
myeloproliferative disorder (1 paper, 2012). A clonal hematopoietic stem cell disorder, characterized by proliferation in the bone marrow of one or more of the myeloid (i.e., granulocytic, erythroid, megakaryocytic, and mast cell) lineages. "Like the other members of FGF family grouped in cluster 2, FGF5 is involved in cell survival activities, while FOP was originally discovered as a fusion partner with FGFR1 in oncoproteins that give raise to stem cell myeloproliferative disorders." (PMID 23107425, 2012).
myocardial ischemia (1 paper, 2024). A disorder of cardiac function caused by insufficient blood flow to the muscle tissue of the heart. "Administration of the FGF5 gene via the coronary arteries was reported to improve blood flow and cardiac function in patients with myocardial ischemia." (PMID 38689297, 2024).
myxoid liposarcoma (1 paper, 2015). A liposarcoma characterized by the presence of round non-lipogenic primitive mesenchymal cells and small signet ring lipoblasts within a myxoid stoma with a branching vascular pattern. "Several FGFs are described to promote neoangiogenesis, among them FGF2 but also FGF5 and FGF18, for which an overexpression in myxoid liposarcomas was detected in this study." (PMID 26036639, 2015).
Obstructive azoospermia (1 paper, 2019). Absence of any measurable level of sperm in his semen, resulting from post-testicular obstruction or retrograde ejaculation. "In this study, we aimed to evaluate the effect of fibroblast growth factor-5 (FGF5), a novel growth factor downregulated in Sertoli cells from Sertoli cell-only syndrome (SCOS) patients compared to Sertoli cells from obstructive azoospermia (OA) patients, on SSCs." (PMID 30670081, 2019).
orofacial cleft (1 paper, 2019). A disorder of facial skeleton that is characterized by cleft lip and/or cleft palate that result in feeding, speech and hearing problems caused by failures during development. "For example, previous studies show that SNPs in the miRNA-binding sites of MSX1, FGF2, FGF5 and FGF9 are associated with the susceptibility of nonsyndromic orofacial clefts." (PMID 31122291, 2019).
ovarian carcinoma (1 paper, 2022). A malignant neoplasm originating from the surface ovarian epithelium. "In addition, qRT-PCR results revealed the expression of CDK4, FGF5, MEIS1, and TES genes was significantly increased in CFP1-deleted ES-2 ovarian cancer cells." (PMID 35864225, 2022).
Pan (1 paper, 2025). "Pan-cancer survival analysis revealed that increased FGF5 expression was associated with a higher hazard ratio (HR) for disease-free interval (DFI) in HNSC patients." (PMID 40001587, 2025).
periodontitis (1 paper, 2021). An acute or chronic inflammatory process that affects the tissues that surround and support the teeth. "Additionally, FGF-5 (40.0% vs 25.4%, p=0.03) and LIF (14.7% vs 5.9%, p=0.04) were detected more frequently in participants with periodontitis." (PMID 34385358, 2021).
skin abnormalities (1 paper, 2020). "The increased expression of keratin genes and FGF5 supports reports of skin abnormalities in DSLD." (PMID 33028365, 2020).
spondylolisthesis (1 paper, 2026). A condition in which there is forward displacement of a vertebral bone over the on below it. "IP MR identified risk-increasing associations for LSS (4E-BP1 and interleukin-4), spondylolisthesis (CXCL1, CXCL5, FGF-5, IL-15RA, and IL-4) and IDD (IL-20RA and IL-6), while IL-18 showed a protective association with IDD that remained robust after multiple-testing correction." (PMID 42317351, 2026).
cancer (49 papers, 2011 to 2025). A tumor composed of atypical neoplastic, often pleomorphic cells that invade other tissues. "Cancer-associated fibroblasts (CAFs), for instance, secrete FGF5, which binds to FGFR2 on NPC cells and activates the Keap1–Nrf2–HO-1 axis." (PMID 40867889, 2025). "For instance, FGF5 derived from cancer-associated fibroblasts can activate FGFR2 on tumor cells, initiating downstream Keap1/Nrf2/HO-1 signaling and enhancing resistance to ferroptosis." (PMID 40867889, 2025). "Among these, genes positively associated with mitogenic activities and cancer progression include FGF5, FOSL1, and FST (endcoding follistatin that belongs to the TGF-β superfamily)." (PMID 38612755, 2024). "Previous studies have found that FGF5 is mainly associated with cancer and hair growth." (PMID 39563941, 2024). "Therefore, these aptamers have the potential to be therapeutic agents for FGF5-associated cancers and hair loss." (PMID 33536494, 2021). "Furthermore, we propose that cancer-associated fibroblasts (CAFs), which are more resistant to radiation and chemotherapy, may serve as a compensatory source of FGF5 in the tumor microenvironment, sustaining tumor cell survival and migration under treatment stress." (PMID 40001587, 2025). "The list of pro-migratory proteins hypersecreted by endothelial cells in response to HT serum or transcripts up-regulated in cancer cells exposed to endothelial-cell-derived HT-CM also includes bFGF, FGF5, and TGF-β1." (PMID 39595551, 2024). "These cells are involved in the regulation of the TME through the secretion of activin A, FGF5, and the production of fibrillar collagen, which supports and promotes the expansion of cancer stem cells and self-renewal of cancer stem cells." (PMID 38715921, 2024). "In triple-negative BC models, SHH ligand produced by cancer cells reprograms CAFs to generate a supportive niche to acquire a chemo-resistant, cancer stem cell phenotype through FGF-5 expression and production of fibrillar collagen." (PMID 37046676, 2023). "In marked contrast, a very recent study using murine models of TNBC found that Hh signaling in CAFs promotes cancer stem cell plasticity and chemoresistance in cancer cells via elevation of stromal FGF5 production." (PMID 31067787, 2019). "MiRNA-188-5p suppresses cancer cell proliferation and metastasis in vitro and in vivo by interacting with fibroblast growth factor 5 (FGF5)." (PMID 29951542, 2018). "FGF‐5, another protein elevated in LLV patients, is part of the fibroblast growth factor family and has been associated with tumour progression and poor prognosis in various cancers, including HCC." (PMID 40078069, 2025). "Pedigree studies based on the UPDB have previously provided the identification of BRCA1 and BRCA2, and more recently have identified additional rare cancer predisposition variants (GOLM1; CELF4; FANCM; ERF; LRBA; FGF5) in similar sets of sampled high-risk pedigrees." (PMID 38136396, 2023). "FGF5 has been discussed in many other cancers and has multiple roles in cancer development." (PMID 33802841, 2021). "MiR-188-5p in HCC suppresses cancer cell proliferation by directly targetting FGF5." (PMID 30910841, 2019). "This may indicate that the abnormal expression of FGF5 in cancer cells may be due to alterations in E-cadherin expression in these cells." (PMID 21197469, 2011). "Therefore, development of an FGF5-specific inhibitor may be value as a hair growth enhancer and for treatment of FGF5-induced cancers; this would also contribute to understanding the mechanism of FGF5-induced signal transduction." (PMID 33536494, 2021). "Fibroblast growth factor 5 (FGF5) is a crucial regulator of hair growth and an oncogenic factor in several human cancers." (PMID 33536494, 2021). "The majority of the DEGs, e.g., SOX11, TBX21, FAM3B, FGF5, HNF1A, MYB, and PLAC8 have been reported to function as promoters or biomarkers in various cancer types." (PMID 34440579, 2021).
cancer (continued). "FZD8, plasminogen activator, urokinase receptor, ITGA2, WNT2B, TIMP3, WNT5B, FGF5, heparanase, HBEGF and WNT3A were up-regulated in the proteoglycan pathways in cancer, whereas WNT10A, PIK3R3, IGF2 were down-regulated." (PMID 30482199, 2018). "They secrete TGF-β, leukemia inhibitory factor (LIF), growth arrest-specific protein 6 (GAS6), fibroblast growth factor 5 (FGF5), growth differentiation factor 15 (GDF15), and hepatocyte growth factor (HGF), which drive the invasive and proliferative behaviors in cancer cells." (PMID 40313969, 2025). "The production of TGFβ, leukaemia inhibitory factor (LIF), growth arrest-specific protein 6 (GAS6), fibroblast growth factor 5 (FGF5), growth differentiation factor 15 (GDF15) and hepatocyte growth factor (HGF) promotes invasive and proliferative behaviour in cancer cells." (PMID 31980749, 2020). "Furthermore, two recent studies demonstrate the promotion of cancer stem cell features by CAF subpopulations expressing CD10/Gpr77 and Hedgehog target genes such as Fgf5, respectively." (PMID 30514914, 2018). "However, a connection between GPC4 and FGF5 or TGF-β in cancer patients has never been reported before." (PMID 38612755, 2024). "Moreover, the production of TGFβ, leukemia inhibitory factor (LIF), growth arrest-specific protein 6 (GAS6), fibroblast growth factor 5 (FGF5), growth differentiation factor 15 (GDF15), and hepatocyte growth factor (HGF) promotes invasive and proliferative behavior in cancer cells." (PMID 34646829, 2021). "Fifteen members of cancer pathways, including FOS, TGFα, FZD8, MMP1, laminin subunit gamma 2, PTGS2, laminin subunit beta 3, ITGA2, laminin subunit alpha 3, VEGFC, WNT2B, heat shock protein 90 beta family member 1, WNT5B, FGF5 and WNT3A, were up-regulated in the MC group." (PMID 30482199, 2018).
tumor (42 papers, 2010 to 2025). "The oncogenic factor FGF5 is implicated in cell growth, morphogenesis, and tumor invasion, whereas PGF is known to enhance cell population proliferation." (PMID 40520894, 2025). "The integration of DNA methylation and gene expression data underscores the importance of FGF5-associated pathways, such as actin cytoskeleton regulation and cAMP signaling, in driving tumor recurrence." (PMID 40001587, 2025). "The consistent identification of FGF5-associated pathways underscores its potential as a diagnostic marker and therapeutic target for mitigating tumor recurrence." (PMID 40001587, 2025). "Another study linked high TGFβ2 and FGF5 expression to NFkappaB activation in tumor cell lines from various malignancies including prostate and cervix cancer." (PMID 29152117, 2017). "Patients with higher FGF5 expression exhibited shorter DFIs, indicating that FGF5 not only serves as a marker of recurrence risk but may also reflect the tumor’s inherent aggressive characteristics." (PMID 40001587, 2025). "Future research should focus on validating FGF5 as a prognostic marker and exploring targeted therapies that disrupt FGF5 signaling in both tumor cells and the tumor microenvironment." (PMID 40001587, 2025). "Reduced methylation at the FGF5 locus in recurrent NPC samples correlated with increased gene expression, suggesting that epigenetic dysregulation of FGF5 contributes to treatment resistance and tumor progression." (PMID 40001587, 2025). "Functional experiments revealed that FGF5 promotes tumor cellmigration, and invasion, while its downregulation enhances radiosensitivity in NPC." (PMID 40001587, 2025). "Protein–protein interaction network analysis further supported the central role of FGF5 in regulating cellular processes related to tumor recurrence." (PMID 40001587, 2025). "FGF-5 is a glycosaminoglycan-binding protein that plays roles in embryonic development, cell proliferation, morphogenesis, tissue repair, and tumor progression." (PMID 41301428, 2025). "In vivo experiments further confirmed that FGF5 downregulation enhanced radiosensitivity, as evidenced by reduced tumor growth in xenograft models." (PMID 40001587, 2025). "FGF5, a member of the fibroblast growth factor superfamily, is involved in multiple human biological processes, such as cell growth, morphogenesis, tumor growth and invasion, tissue repair, and inflammatory processes." (PMID 38988665, 2024). "This reprogramming allowed tumour cells to acquire chemoresistance and a tumour stem cell phenotype through the expression of FGF5 and the production of fibrillar collagen." (PMID 40135140, 2024). "Our findings indicate that tumor cells with high m7G scores exert significant autocrine and paracrine effects on the cellular communication network through multiple tumor growth-promoting signals (FGF5 and SEMA3C) and immunosuppressive signals (MIF and TGF-β)." (PMID 37868988, 2023). "Knockout of FGF5 inhibited OS cell proliferation and tumor growth in a nude mouse model, and the addition of exogenous recombinant FGF5 to OS cells promoted cell proliferation while inhibiting cell apoptosis." (PMID 33536494, 2021). "Quantitative RT-PCR (RT-qPCR) revealed that genes representing mesodermal (T, Kdr), endodermal (Foxa2, Gata4/6, Sox17) and ectodermal (Fgf5, Sox11 for primitive ectoderm) differentiation were generally activated in tumor." (PMID 33468253, 2021). "Among them, FGF6 and FGF5 are growth factors from the fibroblast growth factors signaling pathway, which are well known players contributing to tumor progression." (PMID 31568528, 2019). "Our method recovered transcriptional regulatory alterations at known oncogenes (FGF5) and at cell biological pathway genes that are important for tumor cell biology (ZFAS1 and tumor cell invasion)." (PMID 28333948, 2017). "More recently, FGF5 was identified as a critical target of the tumor suppressive microRNA-188-5p in hepatocellular carcinoma." (PMID 29152117, 2017).